TCF4 (transcription factor 4)
Description:
Transcription factor that binds to the immunoglobulin enhancer Mu-E5/KE5-motif. Involved in the initiation of neuronal differentiation. Activates transcription by binding to the E box (5'-CANNTG-3'). Binds to the E-box present in the somatostatin receptor 2 initiator element (SSTR2-INR) to activate transcription (By similarity). Preferentially binds to either 5'-ACANNTGT-3' or 5'-CCANNTGG-3'.
Synonyms: TCF-4; bHLHb19; ITF-2; SEF-2; ITF2; SEF2; SEF2-1B; E2-2; CDG2T; FCD2; FECD3; PTHS; SEF2-1; SEF2-1A; SEF2-1D
Tractability: Small molecule: a high-quality ligand is known. PROTAC: ubiquitination databases record sites on it; its protein half-life has been measured; a small molecule that binds it is known.
Gene: Protein-coding gene on chromosome 18 (55,222,185 to 55,664,787, reverse strand). Ensembl gene ENSG00000196628.
Subcellular location: Nucleus
Subcellular location (Human Protein Atlas): Cytosol; Nucleoplasm; Predicted to be secreted
Pathways (Reactome):
Signal Transduction: Formation of the beta-catenin:TCF transactivating complex; TGFBR3 expression
Chromatin organization: CHD1 and CHD2 subfamily
Developmental Biology: Myogenesis
Gene Ontology:
Molecular function: DNA binding; DNA-binding transcription factor activity; identical protein binding; protein binding; RNA polymerase II cis-regulatory region sequence-specific DNA binding; sequence-specific double-stranded DNA binding; DNA-binding transcription activator activity, RNA polymerase II-specific; DNA-binding transcription factor activity, RNA polymerase II-specific; E-box binding; protein heterodimerization activity; TFIIB-class transcription factor binding; chromatin binding; protein dimerization activity; RNA polymerase II transcription regulatory region sequence-specific DNA binding; transcription corepressor activity
Biological process: positive regulation of DNA-templated transcription; positive regulation of neuron differentiation; positive regulation of transcription by RNA polymerase II; protein-DNA complex assembly; regulation of transcription by RNA polymerase II; negative regulation of DNA-templated transcription
Cellular component: beta-catenin-TCF complex; beta-catenin-TCF7L2 complex; chromatin; nucleoplasm; nucleus; transcription regulator complex; RNA polymerase II transcription regulator complex
Genetic constraint (gnomAD): Loss-of-function variants: 3 observed, 80.72 expected, observed/expected ratio (o/e) 0.0372, 90% interval 0.016 to 0.096. The upper end of that interval is the gene's LOEUF score, 0.096, which puts it in group 1 of 6, group 1 being the genes least tolerant of losing a copy. Missense variants: 511 observed, 883.56 expected, observed/expected ratio (o/e) 0.58, 90% interval 0.54 to 0.62. Synonymous variants: 275 observed, 323.85 expected, observed/expected ratio (o/e) 0.85, 90% interval 0.77 to 0.94.
Gene-disease validity (ClinGen):
ClinGen rates the evidence that TCF4 causes each of these diseases.
Pitt-Hopkins syndrome (autosomal dominant): Definitive. Pitt-Hopkins syndrome (PHS) is characterized by the association of intellectual deficit, characteristic facial dysmorphism and problems of abnormal and irregular breathing.
Homologues: Orthologues: macaque TCF4 (100% identical), chimpanzee TCF4 (99% identical), dog TCF4 (99% identical), pig TCF4 (99% identical), mouse Tcf4 (98% identical), rat Tcf4 (98% identical), rabbit TCF4 (96% identical), guinea pig TCF4 (92% identical), tropical clawed frog tcf4 (89% identical), zebrafish TCF4 (57% identical), Drosophila melanogaster da (29% identical), Caenorhabditis elegans hlh-2 (16% identical). Paralogues in human: TCF12 (62% identical), TCF3 (52% identical).
Diseases named in the same sentence as TCF4 in open-access papers:
TCF4 is named in the same sentence as 260 diseases in open-access papers, as found by Europe PMC text mining. Sharing a sentence is not in itself a finding about the gene and the disease. The quoted sentences say what the papers report.
schizophrenia (124 papers, 2011 to 2026). A major psychotic disorder characterized by abnormalities in the perception or expression of reality. "TCF4, a human ortholog of Da, is associated with the intellectual disability syndrome Pitt–Hopkins syndrome and schizophrenia." (PMID 41500834, 2026). "Mutations in human TCF4 gene lead to intellectual disabilities such as Pitt–Hopkins syndrome and TCF4 has also been linked to schizophrenia." (PMID 41500834, 2026). "Common genetic variants in TCF4 also confer risk for schizophrenia and related psychiatric disorders." (PMID 42238855, 2026). "As a result of the study, associations of the polymorphic variant TCF4 rs2958182 and TCF4 rs9636107 with the leading symptoms of schizophrenia were discovered for the first time in Caucasian populations of the Siberian region." (PMID 41226544, 2025). "Further study of polymorphic variants of the TCF4 gene opens up prospects for further search for genetic markers of schizophrenia and a deeper understanding of the nature of psychotic disorders." (PMID 41226544, 2025). "In the first stage of the study, groups of schizophrenia patients and healthy individuals were compared for selected TCF4 gene polymorphisms." (PMID 41226544, 2025). "Further elucidation of the causal relationship between polymorphic variants, TCF4 gene regulation, and clinical heterogeneity, progression, and outcome is important for understanding the pathogenesis of schizophrenia." (PMID 41226544, 2025). "Mutations in the human Tcf4 gene (ID 6925), located on chromosome 18, have been associated with schizophrenia, autism spectrum disorder and Pitt-Hopkins syndrome." (PMID 40149012, 2025). "In 2016, a team of authors led by Chow T.J. found an association of the TCF4 rs8766 polymorphic variant with an early age of schizophrenia onset, but the statistical significance of these results disappeared after adjusting for false positives." (PMID 41226544, 2025). "The GWAS variants represented a complex interaction profile, as exemplified by one schizophrenia-associated GWAS variant (rs1261117) that interacted with the promoter of the differentially expressed TF gene TCF4 (transcription factor 4) at all time points." (PMID 39948187, 2025). "The polymorphic variant TCF4 rs2958182, as shown in samples in the European and Chinese populations, is part of the locus of predisposition to schizophrenia." (PMID 41226544, 2025). "In humans, TCF4 has already frequently been implicated in a number of psychiatric and neurological disorders such as schizophrenia, bipolar disorder, MDD, PTSD and autism." (PMID 40087272, 2025). "Most mutations in the Tcf4 gene are either associated with the development of serious nervous system disorders, such as Pitt-Hopkins syndrome or schizophrenia, or are lethal." (PMID 40149012, 2025). "Groups of schizophrenia patients and healthy individuals were compared for selected TCF4 gene polymorphisms." (PMID 41226544, 2025). "The study of genetic variability of TCF4 in schizophrenia of the Southern Chinese Han population identified associations with positive and negative symptoms, but these associations were not corrected for multiple testing." (PMID 41226544, 2025). "Altered Tcf4 function has also been linked to schizophrenia and mice in which Tcf4 is overexpressed develop cognitive impairment, which is attenuated by exercise." (PMID 38217668, 2024). "Forrest M.P., Hill M.J., Kavanagh D.H., Tansey K.E., Waite A.J.,Blake D.J. The psychiatric risk gene transcription factor 4 (TCF4)regulates neurodevelopmental pathways associated with schizophrenia,autism, and intellectual disability." (PMID 39722673, 2024). "TCF4 has been associated with several psychiatric conditions, such as major depressive disorder, schizophrenia, and autism spectrum disorders." (PMID 38827438, 2024).
schizophrenia (continued). "Hill M.J., Killick R., Navarrete K., Maruszak A., McLaughlin G.M.,Williams B.P., Bray N.J. Knockdown of the schizophrenia susceptibilitygene TCF4 alters gene expression and proliferation of progenitorcells from the developing human neocortex." (PMID 39722673, 2024). "Research has shown that TCF4 is a key regulator of neural function and is closely associated with neurodevelopmental disorders such as intellectual disability and schizophrenia." (PMID 39188714, 2024). "Polymorphisms in TCF4 have been associated with risk-taking and adventurousness, alcohol consumption, schizophrenia, depression, and neuroticism; TCF4 is also a non-GWAS candidate gene for other psychiatric and neurological conditions." (PMID 37173343, 2023). "The discovery of TCF4 (T cell factor 4) has been found to be significantly linked with schizophrenia." (PMID 37780577, 2023). "While variants in the TCF4 gene have been associated with neurological disorders, such as schizophrenia, and bipolar disorder, in GWASs, one has been specifically linked to Fuchs endothelial corneal dystrophy (FECD)." (PMID 37761846, 2023). "In this study, we focus on Transcription factor 4 (TCF4), a gene strongly associated not only with the risk of developing schizophrenia but also bipolar disorder and major depressive disorder." (PMID 36171421, 2022). "Changes in the TCF4 gene are linked to the development of many severe neurocognitive disorders such as schizophrenia, intellectual disability, post-traumatic stress disorder, and depression." (PMID 36407762, 2022). "Several whole genome association studies have also revealed that TCF4 is one of the most reproducible susceptibility genes in neurodevelopmental disorders, including schizophrenia (SCZ), Pitt-Hopkins syndrome, autism, and bipolar disorder." (PMID 35965434, 2022). "TCF4 gene variants have been associated with neuropsychiatric diseases such as schizophrenia, bipolar disorder, post-traumatic stress disorder, and major depressive disorder." (PMID 35501322, 2022). "Large GWAS studies have repeatedly identified several non-coding SNPs in the 5’ located introns of the TCF4 gene that contribute to an increased risk of schizophrenia." (PMID 36449485, 2022). "Transcription Factor 4 (TCF4) has been associated with autism, schizophrenia, and other neuropsychiatric disorders." (PMID 35501322, 2022). "Aberrations in the TCF4 gene are associated with several neurocognitive disorders such as schizophrenia, intellectual disability, post-traumatic stress disorder, depression, and Pitt-Hopkins Syndrome, a rare but severe autism spectrum disorder." (PMID 36407762, 2022). "Genetic variants within or near the transcription factor 4 gene (TCF4) are robustly implicated in psychiatric disorders including schizophrenia." (PMID 35965434, 2022). "TCF4 was repeatedly validated as a susceptibility gene for schizophrenia, and TIE1 was implicated with vascular development and pathogenesis of vascular diseases." (PMID 34931221, 2022). "Findings from the master regulator analyses affirm previously reported relationships between neuropsychiatric disorders and mutations of TCF4 that have been implicated not only in depression, but also in schizophrenia and autism." (PMID 35796185, 2022). "The schizophrenia-risk gene Tcf4 has been widely studied in the context of brain development using mouse models of haploinsufficiency, in utero knockdown and embryonic deletion." (PMID 34564703, 2021). "Transcription factor 4 (TCF4) is a crucial regulator of neurodevelopment and has been linked to the pathogenesis of autism, intellectual disability and schizophrenia." (PMID 34184026, 2021). "Variants in TCF4 have been associated with schizophrenia, autism and intellectual disability and TCF4 haploinsufficiency causes the neurodevelopmental disorder Pitt–Hopkins syndrome (PTHS) (OMIM 610954)." (PMID 34184026, 2021).
schizophrenia (continued). "Previous GWAS identified TCF4 polymorphisms linked with schizophrenia and other psychiatric conditions as well as non-neurological genetic diseases." (PMID 34667144, 2021). "The aberrations in TCF4 are associated with neurodevelopmental disorders including schizophrenia, intellectual disability, and Pitt-Hopkins syndrome, an autism-spectrum disorder characterized by developmental delay." (PMID 34748727, 2021). "Among the 25 modules identified, one module was semi-conserved at relapse (DarkTurquoise) and was enriched with risk genes for schizophrenia, showing a dysregulation of the TCF4 gene network in the module." (PMID 34667144, 2021). "Autosomal dominant mutations and deletions in TCF4 cause the neurodevelopmental disorder Pitt-Hopkins syndrome, while common variants at the TCF4 locus are associated with schizophrenia risk." (PMID 33568722, 2021). "Among these genes, the member of the helix–loop–helix family transcription factor 4 (TCF4)—one of the leading schizophrenia risk genes —stands out." (PMID 34667144, 2021). "Tcf4 is a basic helix–loop–helix (bHLH) TF implicated in schizophrenia, autism and Pitt–Hopkins syndrome." (PMID 34564703, 2021). "TCF4 has been shown to affect neurodevelopment and play an important role in cognition, being associated with both schizophrenia and autism-spectrum intellectual disability in addition to PTHS." (PMID 34576033, 2021). "Haploinsufficiency of TCF4 causes a rare neurodevelopmental Pitt-Hopkins syndrome, TCF4 has been linked to schizophrenia and mild to moderate intellectual disability, and has been shown to regulate neurogenesis, synaptic plasticity, memory and DNA methylation." (PMID 34518368, 2021). "GWAS studies have identified SNPs in TCF4 susceptible to schizophrenia and corneal endothelial dystrophy." (PMID 34680902, 2021). "Tcf4 has been implicated in several neurodevelopmental diseases, like autism and schizophrenia, and loss of one copy of Tcf4 leads to major brain malformations resulting in Pitt–Hopkins Syndrome in humans." (PMID 33804772, 2021). "Large-scale genome-wide association studies revealed single nucleotide polymorphisms in TCF4 among the highest risk loci for schizophrenia (SCZ)." (PMID 32641419, 2020). "More subtle alterations in TCF4 gene expression have been linked to non-syndromic intellectual disability, schizophrenia, and bipolar diseases." (PMID 32765228, 2020). "TCF4 gene is implicated in susceptibility to schizophrenia, and mutations in TCF4 cause Pitt-Hopkins syndrome, a rare developmental disorder characterized by severe motor and mental retardation." (PMID 33116252, 2020). "Altered TCF4 gene expression has been linked to non-syndromic intellectual disability, schizophrenia, and a severe neurodevelopmental disorder known as Pitt-Hopkins syndrome." (PMID 32765228, 2020). "TCF4 plays important roles in development and TCF4 gene dysfunction has been implicated in multiple neurodevelopmental diseases including Pitt-Hopkins syndrome and schizophrenia by GWAS24–26." (PMID 31959800, 2020). "Rare TCF4 single nucleotide variants have been described in schizophrenia patients whose symptoms include impairments of attention, memory, social cognition, and executive functions." (PMID 32765228, 2020). "Although these variants and genes were all implicated in schizophrenia in research studies, only two polymorphisms (HTR2A rs6311 and TCF4 rs9960767) were also reported to be associated with schizophrenia at a meta-analytic or genome-wide level of evidence." (PMID 33324248, 2020). "TCF4 deletions have also been detected in patients with autism-spectrum disorders and common gene variants appear associated with an increased risk of schizophrenia." (PMID 32266943, 2020). "Mammalian transcription factor 4 (TCF4) has been linked to schizophrenia and intellectual disabilities, such as Pitt–Hopkins syndrome (PTHS)." (PMID 32641419, 2020).
schizophrenia (continued). "The transcription factor TCF4 was confirmed in several large genome-wide association studies as one of the most significant schizophrenia (SZ) susceptibility genes." (PMID 33037178, 2020). "Considering that alterations in TCF4 are associated with syndromic and non-syndromic forms of intellectual disability, schizophrenia and autism in humans, our findings point to the possibility of an oligodendroglial contribution to these disorders." (PMID 32266943, 2020). "The variant rs9960767, located in intron 3 of the TCF4 gene on chromosome 18q21.1, was significantly associated with schizophrenia in the European population." (PMID 31191620, 2019). "The TCF4 gene was highly associated with schizophrenia in a recent GWAS analysis (Schizophrenia Psychiatric Genome-Wide Association Study [GWAS] Consortium, 2011)." (PMID 31191620, 2019). "The aim of our study was to assay the association of TCF4 single nucleotide polymorphisms (SNPs) with schizophrenia and the effect of these SNPs on phenotypic variability in schizophrenia in Southern Chinese Han Population." (PMID 31191620, 2019). "Among the investigated sets, the TCF4 gene set was the most strongly associated with schizophrenia, with a Stouffer’s Zp-value of 1.18 × 10−46." (PMID 31078131, 2019). "This study showed that several of the target putative core gene-sets investigated were highly significantly associated with schizophrenia, with the strongest effect being observed for the TCF4 core gene set." (PMID 31078131, 2019). "More SNPs, which suggested by GWAS in TCF4 should be included in the further research for insights to the risk of TCF4 in schizophrenia." (PMID 31191620, 2019). "SNPs in the gene transcription factor 4 (TCF4) are genome-wide significantly associated with risk for schizophrenia, and haploinsufficiency of this gene causes Pitt–Hopkins syndrome, associated with severe cognitive deficits and risk for psychosis." (PMID 31078131, 2019). "Given the association of TCF4 variants with schizophrenia and other neurodevelopmental disorders, we examined the enrichment of TCF4 targets with genes associated with different diseases." (PMID 29228394, 2018). "In contrast, a gain of function in Tcf4 is associated with a higher risk in developing schizophrenia." (PMID 29933371, 2018). "We found that TCF4 target genes cluster in neurodevelopmental pathways and are enriched for schizophrenia, ASD, and ID risk genes." (PMID 29228394, 2018). "Clearly, further research will be required to unravel the functional effects of cis-acting variants at the CHRNA5/A3/B4 locus with TCF4 and other transcriptional regulators in schizophrenia and other neurodevelopmental disorders." (PMID 29228394, 2018). "Numerous GWASs repeatedly reported the association of TCF4 with schizophrenia, strongly suggesting that TCF4 is a causal gene for schizophrenia." (PMID 29540662, 2018). "Among the 41 prioritized causal genes, CNTN4, GATAD2A, GPM6A, MMP16, PSMA4, and TCF4 represent the most promising causal genes for schizophrenia." (PMID 29540662, 2018). "Here, we used immunohistochemical analysis to systematically investigate the expression of the intellectual disability and schizophrenia-associated Tcf4 gene in the developing and adult murine CNS." (PMID 29588831, 2018). "Common genetic variants in and around the gene encoding transcription factor 4 (TCF4) are associated with an increased risk of schizophrenia." (PMID 29228394, 2018). "We do not find significant differences in the percentages of proteins associated with ID, ASD or schizophrenia between the interactomes of starting transcription factors Tcf4, Olig2, Npas3, Sox2 (P-value >0.2 for all MD categories)." (PMID 28375211, 2017). "The human TCF4 gene is implicated in susceptibility to schizophrenia and TCF4 haploinsufficiency is the cause of the Pitt-Hopkins mental retardation syndrome." (PMID 27752241, 2016).